MVP (major vault protein)
Diseases named in the same sentence as MVP in open-access papers (continued):
Sharing a sentence is not in itself a finding about the gene and the disease.
epilepsy (3 papers, 2014 to 2023). A brain disorder characterized by episodes of abnormally increased neuronal discharge resulting in transient episodes of sensory or motor neurological dysfunction, or psychic dysfunction. "Previous studies of MVP focused on tumors, drug resistance, and epilepsy; however, the roles of MVP in alcohol dependence or depression have not been reported." (PMID 37547216, 2023). "The prognostic potential of MVP in diseases other than cancer, such as epilepsy, is also noteworthy, as shown in a study reporting MVP and BCRP upregulation in surgical resections from drug-resistant epilepsy patients, which was suggested to be predictive of pathology-specific phenotypes." (PMID 33572350, 2021). "While addressing the transporter hypothesis our study also could not show a role of ABCG2 variants with AED-resistance in epilepsy, and similar lack of association was also observed with from non-ABC transporters, such as major vault protein." (PMID 24586633, 2014).
asthma (2 papers, 2018 to 2025). "In terms of interactions with YPEL4, specific inhibitors of MVP may allow the MAPK pathway to work alongside the PI3K pathway simultaneously, suggesting that specific inhibitors of MVP may serve as therapeutic targets for asthma by promoting the activity of YPEL4." (PMID 39858200, 2025). "It is possible that a specific inhibitor of MVP in terms of its interaction with YPEL4 would allow the MAPK pathway to simultaneously work with the PI3K pathway, suggesting that a specific MVP inhibitor would serve as a therapeutic target in asthma by promoting the activity of YPEL4." (PMID 29892964, 2018).
cervical tumors (2 papers, 2009 to 2012). "The aim of the present study was to assess the relation between the expression of the Major Vault Protein and tumor hypoxia in clinical cervical tumors." (PMID 19660100, 2009). "The aim of the present study was to assess the relation of Major Vault Protein expression and tumor hypoxia in clinical cervical tumors." (PMID 19660100, 2009). "In that sense, high MVP expression is related to severe hypoxia in clinical cervical tumours." (PMID 22931894, 2012).
depression (2 papers, 2023). "The present study aimed to investigate the interaction between a genetic variant (MVP rs4788186) and depression in adult male Han Chinese with AUD during withdrawal." (PMID 37547216, 2023). "This study, which analyzed a specific gene–environment interaction, demonstrated that carriers of the AA homozygote of MVP rs4788186 may be more susceptible to severe alcohol problems and higher levels of depression during withdrawal." (PMID 37547216, 2023). "Carriers of the AA homozygote of MVP rs4788186 may be more susceptible to severe alcohol problems and higher levels of depression during withdrawal." (PMID 37547216, 2023). "The interaction of alcohol dependence level and MVP rs4788186 accounted for a significant portion of the variance in depression (β = −0.17, p < 0.05)." (PMID 37547216, 2023). "Traditional hierarchical regression analysis was conducted to identify the interaction between MVP rs4788186 and alcohol dependence level for depression." (PMID 37547216, 2023). "Hierarchical regression analysis identified an interaction between MVP rs4788186 and alcohol dependence level for depression (β = −0.17, p < 0.05)." (PMID 37547216, 2023). "MVP duplication, overrepresented in SCZ, is associated with depression (HP:0000716)." (PMID 37486921, 2023). "However, with alcohol exposure, we found a significant effect of MVP rs4788186 on alcohol dependence and depression (β = −0.17, p < 0.05)." (PMID 37547216, 2023). "Although there has been no reported association between MVP gene polymorphisms and depression in alcohol-dependent individuals, MVP plays an essential role in regulating nucleocytoplasmic transport, signaling transduction, cellular differentiation, cell survival, and many neurological diseases." (PMID 37547216, 2023).
esophageal squamous cell carcinoma (2 papers, 2022 to 2023). Esophageal squamous cell carcinoma (ESCC) is a type of esophageal carcinoma (EC) that can affect any part of the esophagus, but is usually located in the upper or middle third. "Here we have identified the major vault protein (MVP) and the B-cell lymphoma-2 (BCL2) gene as two potential factors driving MDR in esophageal squamous cell carcinoma (ESCC)." (PMID 35346194, 2022).
focal epilepsies (2 papers, 2022 to 2023). "As another example, the overexpression of the Major Vault Protein (MVP) gene was reported in the brain tissues of patients with refractory partial epilepsy, subsequent focal epilepsies after ganglioglioma, and frontal lobe epilepsy." (PMID 36579854, 2023).
Hepatic steatosis (2 papers, 2019 to 2024). Steatosis is a term used to denote lipid accumulation within hepatocytes. "MVP deletion in macrophages also exacerbated HFD-induced insulin resistance, hyperlipidaemia and liver steatosis in mice." (PMID 30996248, 2019).
microcephaly (2 papers, 2014 to 2023). A congenital or acquired developmental disorder in which the circumference of the head is smaller than normal for the person's age and sex. "Interestingly, a recent study found that the protein level of MVP became higher at P35, which could explain why the microcephaly phenotype became visible after this point at P45 in our study." (PMID 37968726, 2023).
oral cavity squamous cell carcinoma (2 papers, 2012 to 2025). A squamous cell carcinoma arising from the oral cavity. "The aim of the present study was to assess the expression of MVP in oral cavity squamous cell carcinoma patients, its relation with clinical and pathologic prognostic factors and its role in predicting clinical outcome." (PMID 22931894, 2012). "MVP and IGF-1R expression were related in oral squamous cell carcinoma and conferred reduced long-term survival in patients suffering from advanced stages of the disease." (PMID 22931894, 2012). "However, the underlying mechanisms behind this observation are not understood and the role of MVP in oral cavity squamous cell carcinoma has not been deeply studied, especially in combination with other biological markers." (PMID 22931894, 2012).
osteosarcoma (2 papers, 2021 to 2025). A usually aggressive malignant bone-forming mesenchymal neoplasm, predominantly affecting adolescents and young adults. "Similarly, MVP deficiency in the osteosarcoma U2OS-KO cell line results in slower migration and larger spheroid formation, indicating further MVP’s potential involvement in cell adhesion and metastasis." (PMID 40004027, 2025). "Immunohistochemical staining revealed strong MVP expression in TRAP-positive multinucleated osteoclasts from human developmental bone, osteosarcomas, and giant cell tumors." (PMID 34158848, 2021).
pancreatic carcinoma (2 papers, 2024 to 2025). "Subsequently, we sought to elucidate the relationship between MVP expression and ICI (immune checkpoint inhibitor) therapy, an emerging paradigm in pancreatic carcinoma treatment." (PMID 39026679, 2024).
Papillary Thyroid Cancer (2 papers, 2021 to 2024). "Previous studies have reported that MVP suppresses the progression of papillary thyroid cancer by interfering with the ERK and AKT pathways." (PMID 39026679, 2024).
renal adenocarcinoma (2 papers, 2019 to 2021). "MVP was clearly involved in the process, as its knockdown in human renal adenocarcinoma (ACHN) cells resulted in decreased HIF-1α ubiquitination." (PMID 33572350, 2021). "MVP can also promote the degradation of HIF1α, a known tumor promoting factor, and function as a tumor suppressor in renal adenocarcinoma cells." (PMID 31092229, 2019). "It supports the notion that MVP may function as a tumor suppressor in renal adenocarcinoma cells." (PMID 31092229, 2019).
rheumatoid arthritis (2 papers, 2021 to 2022). A chronic, systemic autoimmune disorder characterized by inflammation in the synovial membranes and articular surfaces. "The protein MVP is largely elevated in rheumatoid arthritis and other inflammatory diseases." (PMID 36203997, 2022). "Finally, serum MVP anti-MVP autoantibodies have also been proposed as biomarkers in rheumatoid arthritis." (PMID 33572350, 2021).
sarcoma (2 papers, 2021 to 2022). A usually aggressive malignant neoplasm of the soft tissue or bone. "Moreover, we found the positive correlation of MVP expression with SI (Doc) and SI (Doc + Gem) in undifferentiated pleomorphic sarcoma samples from patients treated with neoadjuvant chemotherapy." (PMID 35328603, 2022). "In analysis of undifferentiated pleomorphic sarcoma subgroup, we found the positive correlation in MVP expression and resistance to Doc and Doc + Gem combination, and this correlation become stronger in the cells obtained from patients after neoadjuvant chemotherapy." (PMID 35328603, 2022).
alcohol dependence (1 paper, 2023). Physical and psychological dependence on alcohol. "In the next step, the interaction of alcohol dependence level and MVP rs4788186 was included in the regression equation." (PMID 37547216, 2023).
bowel cancer (1 paper, 2025). "Furthermore, spatial transcriptome datasets of bowel cancer tissue samples were analyzed to evaluate the significantly higher levels of MVP transcription in epithelial cell communities." (PMID 39744434, 2025).
brain tumours (1 paper, 2007). "Chemotherapeutic treatment success in brain tumours is mainly limited by the blood–brain barrier and the expression of chemoresistance-related proteins like P-glycoprotein (P-gp), multidrug resistance protein 1 (MRP1), and major vault protein (MVP) also known as lung resistance protein (LRP)." (PMID 17342095, 2007).
breast tumors (1 paper, 2019). "Another important finding is the fact that a gradient of MVP expression is observed between the invasive front and the tumor center of human breast tumors, highlighting that the depicted mechanism observed in vitro also exists in vivo." (PMID 30654824, 2019). "Finally, in a series of human breast tumors, we observed a gradient of MVP expression, which was higher at the invasive front, where tumor cells are at close proximity to adipocytes, than in the tumor center, highlighting the clinical relevance of our results." (PMID 30654824, 2019).
cardiomyopathy (1 paper, 2022). A disease of the heart muscle or myocardium proper. "In our study, the expression of MVP was upregulated in DOX-induced cardiomyopathy which confused us at first." (PMID 35246039, 2022). "To address the contribution of the MVP to AKT in the doxorubicin-induced cardiomyopathy model, we made use of AAV9 to overexpress the MVP and monitored activation of AKT in hearts." (PMID 35246039, 2022). "Adeno-associated virus serotype 9 (AAV9)-mediated overexpression of MVP significantly attenuates cardiomyocyte apoptosis in DiCM through activating AKT, providing a potential cardioprotective target to improve cardiac function from DOX-induced cardiomyopathy." (PMID 35246039, 2022).
colorectal tumor (1 paper, 2021). "Comparative analysis of MVP protein expression level in normal colon tissue, primary colorectal tumor, and metastasis showed that the expression of this protein does not increase significantly in the primary tumor, but its expression increases in metastatic cells." (PMID 34829999, 2021).
dermatomyositis (1 paper, 2022). Dermatomyositis (DM) is a type of idiopathic inflammatory myopathy characterized by evocative skin lesions and symmetrical proximal muscle weakness. "NFYB, GRN and MVP were diagnostically significant for both dermatomyositis and polymyositis in the dataset for inflammatory myopathy." (PMID 36203997, 2022). "In polymyostis and dermatomyositis, MVP and GRN expression levels were significantly higher, while NFYB levels were significantly lower." (PMID 36203997, 2022).
dysferlinopathy (1 paper, 2022). "Consistent with the two datasets, MVP, GRN, and ERP29 expression were significantly upregulated, and RNF128, NFYB, and KPNA3 were significantly downregulated in the dysferlinopathy patients compared with the controls." (PMID 36203997, 2022). "In both datasets, MVP, GRN, and ERP29 showed significantly higher expression levels, while RNF128, NFYB, and KPNA3 had significantly lower expression levels in dysferlinopathy than normal controls." (PMID 36203997, 2022).
head and neck cancer (1 paper, 2012). A primary or metastatic malignant neoplasm affecting the head and neck. "Only one study has reported data of MVP expression in head and neck cancer." (PMID 22931894, 2012).
heart failure (1 paper, 2022). Inability of the heart to pump blood at an adequate rate to meet tissue metabolic requirements. "To explore the role of MVP in cardiomyocyte for the established DOX-induced heart failure model, we used AAV9 system to specifically overexpressed mouse MVP in the myocardial tissues under the cTnT promoter." (PMID 35246039, 2022). "Then we realized that the expression of MVP may be similar to brain natriuretic peptides in heart failure which play a compensatory role." (PMID 35246039, 2022). "In this study, we identified the upregulation of MVP in DOX-induced heart failure model." (PMID 35246039, 2022).
Hyperinsulinemia (1 paper, 2019). An increased concentration of insulin in the blood. "In the present study, we found that MVP deficiency exacerbated HFD-induced high blood glucose and glucose-induced hyperinsulinemia." (PMID 30996248, 2019).
Lewis lung carcinoma (1 paper, 2019). "We further performed shRNA-introduced knockdown of MVP in Lewis lung carcinoma (LLC) cells and examined its effects on the tumor formation in a xenograft mouse model and the tumor cell proliferation, apoptosis, and signal transduction in vitro." (PMID 31092229, 2019).
liver cancer (1 paper, 2023). An epithelial or non-epithelial malignant neoplasm that arises from the liver. "Our previous work demonstrated that MVP expression was significantly increased in liver cancer tissues compared to normal liver tissues; the high expression of MVP was positively associated with poor outcomes in HCC." (PMID 38264642, 2023).
lymph node metastasis (1 paper, 2019). "Consistently, adenocarcinoma patients with higher MVP expression had better prognosis and less lymph node metastasis." (PMID 31092229, 2019).
Macrocephaly (1 paper, 2022). Occipitofrontal (head) circumference greater than 97th centile compared to appropriate, age matched, sex-matched normal standards. "The KCTD13 gene is a key driver of neuronal proliferation in zebrafish and mice and a major driver of the 16p11.2 microdeletion syndrome macrocephaly, and MAPK3 and MVP genes in the deletion region may act as modifier genes to enhance the expression of KCTD13 gene." (PMID 36553582, 2022).
mesothelioma (1 paper, 2016). A usually malignant and aggressive neoplasm of the mesothelium which is often associated with exposure to asbestos. "By comparing these datasets, we found 3 genes that were elevated in 3D compared to 2D as well as in mesothelioma compared to normal tissue: argininosuccinate synthetase 1 (ASS1), annexin A4 (ANXA4) and the major vault protein (MVP)." (PMID 26982031, 2016).
oral cavity carcinoma (1 paper, 2012). A carcinoma arising in the oral cavity. "MVP was overexpressed in 67 (51.1%) of our oral cavity carcinoma patients." (PMID 22931894, 2012).
Osteochondroma (1 paper, 2021). A common, benign cartiliginous neoplasm arising from the metaphysis of bone. "Western blot results showed that expression of GLI1, MVP, P-p70S6K1, and P-AKT were enhanced in conventional CS as compared to the expression in non-malignant normal cartilage and osteochondroma." (PMID 33637972, 2021).
renal carcinoma (1 paper, 2009). A carcinoma arising from the epithelium of the renal parenchyma or the renal pelvis. "It is likely that chemoresistance in RCC is multifactorial, other factors implicated as being involved in the complex chemoresistance mechanisms of RCC include Clusterin; there also is some evidence that lung resistance protein (LRP/MVP) may contribute to inherently resistant renal carcinoma." (PMID 19552816, 2009).
rhabdomyosarcoma (1 paper, 2022). A rare aggressive malignant mesenchymal neoplasm arising from skeletal muscle. "In one study it was demonstrated that MVP protein was predominantly expressed in differentiated cells in rhabdomyosarcoma samples before and after chemotherapy, possibly MVP expression allow rhabdomyosarcoma cells to survive the chemotherapy." (PMID 35328603, 2022).
schizophrenia (1 paper, 2021). A major psychotic disorder characterized by abnormalities in the perception or expression of reality. "While most associations we detected were in the expected direction given previous knowledge, MVP and KCTD13 were associated with BMI in the opposite (positive) direction, and YPEL3 with schizophrenia in the negative direction." (PMID 34715901, 2021).
tongue squamous cell carcinoma (1 paper, 2025). A squamous cell carcinoma that arises from the tongue. "Major vault protein (MVP) plays a contributing role in multifarious cancers, and then its role in Tongue squamous cell carcinoma (TSCC) is uncomprehending." (PMID 40586636, 2025).
triple-negative breast carcinoma (1 paper, 2020). An invasive breast carcinoma which is negative for expression of estrogen receptor (ER), progesterone receptor (PR), and human epidermal growth factor receptor 2 (HER2). "For example, hsa-mir-5684-p3_1ss18CG targeting major vault protein (MVP), which was found to be regulated by Notch1 and contribute to overcome chemoresistance in triple-negative breast cancer cells." (PMID 32293320, 2020).
Uterine leiomyoma (1 paper, 2024). The presence of a leiomyoma of the uterus. "Through proteomics analysis of uterine leiomyoma and uLMS, major vault protein(MVP) immunohistochemistry was found to have a sensitivity of 50% and specificity of 100% in the comparison of uterine leiomyoma and uLMS." (PMID 39472980, 2024).